RDH10 (retinol dehydrogenase 10)
Diseases named in the same sentence as RDH10 in open-access papers (continued):
Sharing a sentence is not in itself a finding about the gene and the disease.
cancer (5 papers, 2015 to 2022). A tumor composed of atypical neoplastic, often pleomorphic cells that invade other tissues. "According to the Ingenuity Pathway Analysis (IPA) database, RDH10 knockdown affected expression of genes involved in cancer, apoptosis, growth and proliferation, motility and cell cycle." (PMID 29285249, 2017). "As predicted, we found that RDH10 regulates a cluster of genes and signaling pathways related to cancer cell proliferation and survival." (PMID 29285249, 2017). "As mentioned under the headings “Molecular characteristics in OCCCs related to anti-oxidative pathway” and “Oxidative stress and cancer stemness of OCCC,” molecules conferring oxidative stress resistance, including HNF1B, SOD2, and RDH10, are deeply implicated in therapeutic refractivity." (PMID 33525614, 2021). "Overall, RDH10 overexpression may imply cancer stemness and tumorigenesis in OCCC, resulting in a difficult prognosis refractory to existing therapies." (PMID 33525614, 2021). "As retinoic acid is used in the treatment of many types of leukemia, it is possible that RDH10, an important enzyme in retinoic acid synthesis, might be involved in cancer development." (PMID 29285249, 2017). "In addition, microarray data demonstrate that RDH10 regulates multiple cancer-related genes and pathways, including the TWEAK –NF-κB axis." (PMID 29285249, 2017). "CD4+CD45RO+ T cells in the lesional blood highly expressed genes relating to cancer progression and CTCL pathogenesis: RGS1, RDH10, HES1, DNAH9, ANK2, and SGK1 16–25." (PMID 34608214, 2021). "Results from a total of 1,911 individual cancer patients demonstrated that the mRNA expressions of RALDH1, ADH1 and RDH10 were highest in HCC patients (dark blue histogram bars)." (PMID 26571119, 2015). "Furthermore, our group recently found that retinol dehydrogenase 10 (RHD10), enzymes related to vitamin A metabolism and gluconeogenesis, can reflect cancer stemness through precise analyses of the RAB39A (a member of the RAS oncogene family)‒RXRB (retinoid X receptor beta) axis." (PMID 33525614, 2021).
infection (3 papers, 2016 to 2022). The state of being infected such as from the introduction of a foreign agent such as serum, vaccine, antigenic substance or organism. "The immune response of Rdh10-deficient CD8+ T cells was investigated in an ovalbumin-expressing Listeria monocytogenes (LM-OVA) infection model." (PMID 35844620, 2022). "T cell-specific Rdh10 deficiency enhanced memory T-cell formation through blocking RAL production in infection model." (PMID 35844620, 2022). "The RDH10 promoter was amplified in cells transduced by AAV2.1-OTX2 when the OTX2 was used but not the anti-rabbit antibodies showing that OTX2 expressed through the use of AAV infection is binding to the RDH10 promoter." (PMID 26985665, 2016). "In contrast, ADAMTS18, CLN8, RDH10 and TNPO1 were shown to be up-regulated following infection in HSaVEC, indicating that gene regulation differs for these genes between the endothelial cells." (PMID 26837541, 2016).
metabolic disorders (2 papers, 2023 to 2025). "Similarly, in the physiological state, RDH10 was expressed in most hepatocytes of the liver, and with increasing metabolic disorders, RDH10 expression decreased significantly, with the most significant decrease in T2DM mice." (PMID 39925846, 2025).
heart disease (1 paper, 2023). "In this study, we demonstrated for the first time the roles of RDH10 on cardiac retinol metabolism and heart disease in adulthood." (PMID 36864033, 2023).
RDH10 also shares sentences with these, for which no sentence is quoted: bladder cancer (2 papers); Hyperglycemia (2); bacteremia (1); choanal atresia (1); colon cancer (1); glioblastoma (1); Hepatic steatosis (1); Listeria infection (1); liver disease (1); lung carcinoma (1); Myocardial fibrosis (1); myocardial hypertrophy (1); psoriasis (1); Retinal diseases (1); Stillbirth (1); Stroke (1); type 1 diabetes (1); viral infection (1).